DDIT3 (DNA damage inducible transcript 3)
Diseases named in the same sentence as DDIT3 in open-access papers (continued):
Sharing a sentence is not in itself a finding about the gene and the disease.
tumor (continued). "Subsequently, the anti-tumor effect of ferrichrome was tested in an AOM-DSS model of carcinogenesis, where it was found to induce apoptosis via the upregulation of DDIT3 (DNA damage inducible transcript 3)." (PMID 34068653, 2021). "Higher levels of Ddit3 mRNA were detected in sorted CD8+ TILs, compared to their splenic counterparts from tumor-bearing or tumor-free mice." (PMID 30894532, 2019). "Elimination of CD8+ T cells restored tumor growth in B16-bearing Ddit3T cell-KO mice, confirming the role of CD8+ T cells in the antitumor responses induced by Ddit3 deletion in T cells." (PMID 30894532, 2019). "Differential expression of seven of these genes (CFD, ALDH18A1, CHKA, DDIT3, ITGA6, PSPH and SQLE) was replicated in another set of 12 paired NASH-HCCs and adjacent non-tumor livers by RT-qPCR (all P < 0.05 by paired t test)." (PMID 30367044, 2018). "Prolonged and notable ER stress can activate the apoptosis signaling pathways by inducing the overexpression of DNA damage-inducible transcript 3, also known as GADD153 or CHOP, and promote tumor cell death." (PMID 30671458, 2018). "We subsequently demonstrated that DDIT3 increased NAG-1 expression in GBM cell lines, which led to tumor cell apoptosis." (PMID 27852055, 2017). "The present study results revealed that DDIT3 and NAG-1 were upregulated, leading to tumor cell apoptosis with K8 treatment." (PMID 27852055, 2017). "DNA damage-inducible transcript 3, also known as C/EBP homologous protein (CHOP), is a key marker for tumor apoptosis." (PMID 23956781, 2013). "In this region, there are important oncogenes such as CHOP (DDIT3), GLI, MDM2, CDK4, SAS, HMGA2, but also the HOXC locus, involved in development and tumor progression." (PMID 24085196, 2013). "We therefore combined the expression values for the genes identified above (DDIT3, HOXD10, PDE1C, PLS3, PTEN and TUSC3) into a single value per tumor sample, termed 'GNS signature score'." (PMID 23046790, 2012). "DNA damage inducible transcript 3 (DDIT3), also known as GADD153 or CHOP, is an endoplasm transcription factor that plays crucial roles in various stress responses and regulates cancer stemness across diverse tumor types 214,215." (PMID 40521202, 2025). "•DDIT3 drives proliferation, inhibits apoptosis, and enhances invasiveness in malignant cells.•Boundary cells in the DCIS-to-invasive transition zone express tumor markers and myoepithelial markers, potentially contributing to tumor progression." (PMID 40867511, 2025). "Researchers have reported an intricate interaction network, wherein DDIT3 regulates a complex interplay of molecular responses within the non-neoplastic cells inhabiting the tumor niche 15,44." (PMID 38911383, 2024). "The role of DDIT3 in the EMT process may be attributed to modulating the expression of adhesive molecules and matrix metalloproteinases, which are involved in tumor cell invasion and metastasis." (PMID 38911383, 2024). "Furthermore, the Spearman rank correlation analysis showed a positive correlation between DDIT3 and ATF3 levels in LUSC and LUAD tumor tissues." (PMID 38244586, 2024). "The top-scoring genes altered in the four gene sets included many genes associated with cell apoptosis and DNA damage, such as GADD45A, DDIT3, BAX, CASP1, CASP8, ATM, and FANCD2, demonstrating that diminishment of RAD51 contributes to the tumor suppressive effect." (PMID 37175611, 2023). "In the HCC TME, DDIT3 and HSP1 may together regulate apoptosis and metabolism to promote tumor cell proliferation and tumor progression." (PMID 35967424, 2022). "The analysis did not detect MDM2 amplification, Rb1 deletion, break apart signals of EWSR1, FUS, DDIT3, or c-myc, or c-myc-IGH fusion signals, but it did detect more c-myc signals in 837 out of 996 tumor cells and 823 out of 1,000 tumor cells." (PMID 36514176, 2022).
tumor (continued). "This confirmed that tumor cells secrete factors that induce mRNA-expression of EIF2AK3, DDIT3, HSPA5, spliced XBP1, and HSPA5, as well as protein expression of p-IRE1α in hepatic stellate cells co-cultured with tumor cells, indicating the presence of ER-stress." (PMID 33103995, 2020). "(A) mRNA expression of ER-stress markers Edem1, Ero1b, Grp94, Herp, Atf4, Eif2ak3, Ddit3, and Hspa5 in liver tissue from healthy mice; and tumor tissue and surrounding non-tumoral tissue from mice with DEN-induced HCC." (PMID 33103995, 2020). "Blocking TGFβ-receptor signaling with SB-431541 significantly reduced mRNA-expression of ER-stress markers DDIT3, spliced XBP1 and HSPA5 in stellate cells co-cultured with tumor cells using transwells." (PMID 33103995, 2020). "So, DDIT3 is usually known as the negative molecule marker of the malignant proliferation of tumor cells." (PMID 31160581, 2019). "On the basis of our microarray data, apoptosis related tumor suppressors PLK3 and DDIT3 were upregulated after HOXA-AS2 inhibition, which elucidated that these two genes may also be key downstream mediators of HOXA-AS2." (PMID 26384350, 2015). "Fluorescence in situ hybridization showed that the tumor cells did not have the DDIT3 alteration or amplification of MDM2." (PMID 25621027, 2015). "Pathologic complete response was observed in 13% of patients as defined by complete absence of FUS-CHOP/DDIT3 translocation-positive tumor cells in the resection specimens." (PMID 24216990, 2013). "However, our in vitro genome‐wide immune screen results showed that knockout of Atf4, Ddit3, Slc7a11, or Slc3a2 alone did not significantly enhance tumor cell sensitivity to T cell–mediated killing." (PMID 41042068, 2025). "Further, we employed SCENIC to predict transcription patterns of tumor cells, finding a series of key TFs of HCC tumorigenesis, such as TFs in regulation of cell dedifferentiation (SPI1, HMGB3, and YBX1) and in abnormal bile acid metabolism (NR1H4, NR1I3, FOXA3 and DDIT3)." (PMID 37985711, 2023). "In selected instances, DDIT3 co-expression with GOSR2 (protein transport) and ASNS (asparagine synthetase) remained coordinated, suggesting that some less-known aspects of DDIT3 activity may benefit tumor cells." (PMID 35237269, 2022). "However, ferrichrome did not exert a significant tumor-suppressive effect in the A2 or C9 organoids (A2: 52.6%, p = 0.15, C9: 40.5%, p = 0.25) despite significantly inducing the DDIT3 expression (A2: 1.62, C9: 1.63)." (PMID 33407519, 2021). "By co-culturing stellate cells with tumor cells, we mainly observed an increase of the IRE1α-branch of the UPR; however, it is important to note that HepG2-cells also significantly induced mRNA-expression of EIF2AK3, while Huh7-cells seemed to induce DDIT3 in the LX2-cells." (PMID 33103995, 2020). "Our analyses showed that the transcriptome associated with RASSF1, a tumor suppressor involved in cell cycle regulation and not previously linked to UPR, is highly correlated with the transcriptome of several UPR‐related genes, such as BiP/GRP78, DNAJB9, GRP94, ATF4, DNAJC3, and CHOP/DDIT3." (PMID 36723232, 2023). "Interestingly DDIT3 co‐expression with GOSR2 (protein transport) and ASNS (asparagine synthetase) remained coordinated, suggesting that some less known aspects of DDIT3 activity may benefit tumor cells." (PMID 34698427, 2021). "Therefore, our microarray analysis results fit well with the known effects of signaling pathways and genes on tumorigenesis, suggesting that the promotion of tumor development by C1QTNF6 might be mediated through regulation of Acute Phase Response signaling and ID1, BBC3, and DDIT3 gene expression." (PMID 34906149, 2021). "It recognizes the N-terminus of DDIT3, so regardless of the fusion partner (FUS or EWSR1), the antibody is expected to recognize tumor-specific oncoproteins." (PMID 39456230, 2024).
tumor (continued). "We note that the relationship between ATF4 and DDIT3, while not consistently perturbed—ATF4 and DDIT3 co‐expression was only significantly perturbed in 5 tumor types (Fig EV4, EV5; UCEC, THYM, THCA, BRCA, and HNSC, respectively)—was also not preserved." (PMID 34698427, 2021). "We found a significantly increased expression of DDIT3, but not DDIT4, in both canine and feline tumoral cells at 6 h post BB-CLA when compared to DMSO-treated, control tumoral cells." (PMID 29649984, 2018). "The tumor was analyzed by fluorescence in situ hybridization (FISH), and revealed the absence of DDIT3 alteration or MDM2 amplification, thus supporting the diagnosis of DFML and excluding a diagnosis of myxoid liposarcoma." (PMID 25621027, 2015). "In this case, the absence of DDIT3 rearrangement and focal expression of CD34 and S100 are consistent with previously reported findings in LLT, supporting its classification within this tumor spectrum." (PMID 41246635, 2025).
cancer (388 papers, 2003 to 2026). A tumor composed of atypical neoplastic, often pleomorphic cells that invade other tissues. "Associations with SPTA1, PIK3CA, and MAP3K1 mutations suggest the role of DDIT3 in diverse pathways in cancer progression." (PMID 38911383, 2024). "The imipramine ONC201 has antiproliferative effects in several cancer cell types and activates integrated stress response pathway associated with the induction of Damage Inducible Transcript 3 (DDIT3, also known as C/EBP homologous protein or CHOP)." (PMID 34088951, 2021). "Expression levels of several previously reported genes implicated in cancer development and progression were altered, such as DDIT3, GATA6, UPP1, FAT3." (PMID 26158411, 2015). "DDIT3 dysregulation has been implicated in several diseases, including cancer." (PMID 38911383, 2024). "Among these factors, DDIT3, also known as CHOP (C/EBPhomologous protein), has previously been shown to be associated with HBV-inducedliver cancers." (PMID 41070968, 2025). "Upregulation of DDIT3/CHOP in malignant tumors compared to benign lesions was confirmed by immunohistochemistry." (PMID 40004005, 2025). "Although the PERK pathway activates pro-apoptotic factors like DNA damage inducible transcript 3 (DDIT3) and B-cell lymphoma-2 (Bcl-2) family proteins, recent reports suggest that in cancer cells the balance is shifted toward pro-survival signaling." (PMID 38672243, 2024). "Normally, DDIT3 is transcribed at low levels but is elevated under cellular stress conditions and is involved in the stress response and cancer process by inducing cell cycle arrest and apoptosis." (PMID 39456230, 2024). "DDIT3 was predominantly expressed within the carcinoma cells, with conspicuous localization within both the cellular nucleus and cytoplasmic compartments." (PMID 38911383, 2024). "DDIT3 also known as C/EBP homologous protein (CHOP) is a specific transcription factor in ER that can activate apoptotic pathways in many conditions such as cancer." (PMID 37448958, 2023). "The summary actions of DDIT3 increase the survival of cancer cells when exogenous glutamine is limited." (PMID 36941538, 2023). "Studies have also shown that DDIT3 can trigger key early events leading to cell apoptosis, which is considered an important target for the development of anti-cancer drugs." (PMID 35211154, 2022). "A recent study discovered the role of DDIT3 in balancing glycolysis and oxidative phosphorylation during glutamine deprivation in cancer cells." (PMID 35967424, 2022). "The discrete but coordinated actions of DDIT3 therefore contribute to metabolic reprogramming, serving to balance glycolysis against oxidative phosphorylation and allowing cancer cells to survive metabolic stress conditions." (PMID 34105294, 2021). "The summary actions of DDIT3 were shown to benefit the long‐term higher survival of cancer cells when exogenous glutamine is limiting." (PMID 34105294, 2021). "Lastly, since many of the mechanistic experiments conducted were performed in the context of a human cancer cell line, we evaluated the growth of WT and DDIT3‐KO HepG2 as xenografts in nude mice fed either a normal or glutamine‐free diet." (PMID 34105294, 2021). "There is an increased expression of ATF4 in cancer cells, and it promotes apoptosis induced by chemotherapeutic drugs by increasing the expression of DNA damage-inducible transcript 3 (DDIT3) 34,35." (PMID 32624694, 2020). "DDIT3 is a protein that induces apoptosis in various types of cancer cells upon endoplasmic reticulum stress." (PMID 29914181, 2018). "Predictably, the drug combinations cooperatively blocked constitutive and Wnt3a-induced SOX4 expressions in cancer cell lines, and this effect was rescued in DDIT3−/− cells." (PMID 29977599, 2018).
cancer (continued). "Overall, the data revealed that isochaihulactone disrupted ER homeostasis in cancer cells by increasing DDIT3 and NAG-1 expression." (PMID 27852055, 2017). "This included the pro-apoptotic Ddit3 and transcription factor Nr2f1, which exerts anti-AP-1 activity and are a mediator of the anti-cancer effect of retinoic acid." (PMID 26427040, 2015). "Characterization of DDIT3 regulated functions helps understanding its role in stress response and involvement in cancer and degenerative disorders." (PMID 22496745, 2012). "Finally, in a separate study performed in cancer cells, acidification induced by metformin indirectly suppresses Wnt signaling by activating the DDIT3 transcriptional repressor, consistent with our data showing low pH suppresses β-catenin stability." (PMID 40526494, 2025). "Notably, HDAC6 inhibition activates DNA damage repair pathways by upregulating cellular stress genes such as DDIT4 (RTP801/Dig2/REDD1) and DDIT3 (CHOP/GADD153), highlighting its potential as a therapeutic target in cancer treatment." (PMID 40843669, 2025). "Elevated levels of SOX4, DDIT3, and GADD45A—genes implicated in stress response, DNA repair, and cancer stem cell maintenance—further suggest engagement of transcriptional mechanisms linked to cancer progression, therapy resistance, and recurrence." (PMID 40756515, 2025). "Previously, researchers have demonstrated the dual role of DDIT3 in malignant tumors." (PMID 38911383, 2024). "The downregulation of the DDIT3/CHOP protein might signify the inhibition of the ERS-induced apoptosis pathways in cancer." (PMID 37448958, 2023). "In addition, outside those mentioned, a group of transcription factors, which dysregulation has been widely associated with cancer phenotype was identified, including DEGs such as BCL6, DDIT3, GADD45A, HMGA2, and ID2." (PMID 35359411, 2022). "Furthermore, DDIT3 overexpression promoted an enrichment in cancer-related signatures, indicating a potential oncogenic role of this TF." (PMID 36494342, 2022). "Thus, activation of glycolysis through DDIT3 during chronic glutamine shortages appears to represent an economical means to maintain ATP levels and supporting long‐term cancer cell survival." (PMID 34105294, 2021). "Unlike chemotherapeutic regimes, these herbs, such as BP and ICH, cause a significant reduction of cancer size via a variety of molecules, such as Nurr77, DDIT3 and NAG-1 without harming healthy cells." (PMID 29385679, 2018). "These and our findings may provide a basis to develop HTS protocols to screen for anti-cancer compounds by means of qPCR-based early detection of DDIT3 and TRIB3 (t = 6 h)." (PMID 29290987, 2017). "Detailed characterization of DDIT3 functions may help understanding its roles in cancer and in diseases involving cell/tissue stress." (PMID 22496745, 2012). "In addition, our findings indicate a role for DDIT3 in cancer stem cells." (PMID 38474084, 2024). "As fusion proteins are gradually showing their potential as targets for precision cancer therapy, FUS::DDIT3 has also been investigated as a therapeutic target." (PMID 39456230, 2024). "(A) mRNA-expression of ER-stress markers ATF6, ATF4, EIF2AK3, GADD34, EDEM1, DDIT3 and HSPA5, in stellate cells (LX2) co-cultured with cancer cells (HepG2 or Huh7) and treated with 4μ8C or control." (PMID 33103995, 2020).
cancer (continued). "Upregulation of the metabolic genes (ALDH18A1, CAD, CHKA, POLD4, PSPH, and SQLE) and aberrant expression of cancer-related genes (ALCAM, ITGA6, DDIT3, MAP3K6, and PAK1) were found in mouse fed with high-fat-high-cholesterol similar to human NASH-HCCs." (PMID 31795276, 2019). "Notable alterations in human cancer gene orthologs impacted by SVs in single cases include an ARHGEF12 inversion, a BIRC3 inversion, a CLPTM1L-TERT translocation, a DDIT3 inversion, a MYO5A translocation, and a TCF12 inversion." (PMID 30188888, 2018). "We demonstrated for the first time the aberrant expression of cancer-related genes (ALCAM, ITGA6, DDIT3, MAP3K6 and PAK1) and metabolism-related genes (ALDH18A1, CAD, CHKA, POLD4, PSPH, SQLE and CFD) in human NASH-HCCs." (PMID 30367044, 2018). "DGIdb mining identified celecoxib, axitinib, and vinblastine, which interact with DDIT3, PDGFB, and JUN, respectively, with minimal interactions with other genes and proven anti-cancer effects." (PMID 27821810, 2016). "The HDAC6 inhibitor tubacin has been shown to promote cell death through the intrinsic apoptotic pathway by inducing the expression of cellular stress genes such as DDIT4 (RTP801/Dig2/REDD1) and DDIT3 (CHOP/GADD153), thereby triggering DNA damage in various cancer cells." (PMID 40843669, 2025). "Specifically, increased DDIT3 heterogeneity is indicative of poor response regardless of the expression phenotypes of the individual cancer cells." (PMID 35169222, 2022). "Among them, BST2, CALR, DDIT3, HSPA5, and TRIB3 were significantly up-regulated in cancer tissues." (PMID 34580365, 2021). "Since DDIT3 showed apparently strong (although non-significant) upregulation (22.37-fold with the Human Cancer Pathway Finder Array and 22.20-fold with the Human DNA Damage Signaling Pathway Array), it was also analyzed by qPCR." (PMID 30451877, 2018). "For instance, DDIT3 (C/EBP homology protein (CHOP)) and ATF3 are markedly upregulated in response to ATF4 activation, particularly under prolonged stress conditions, which eventually leads to cell death in normal as well as cancer cells." (PMID 26657730, 2016). "Moreover, mutations in SPOP, frequently found in PCa, may compromise the function of the DDIT3-SPOP axis, contributing to therapy resistance and more aggressive cancer phenotypes." (PMID 40521202, 2025). "However, it has already been shown that DDIT3 and GADD45A are repressed by NFκB in cancer cells to ensure cell survival and may therefore be important for adaptation." (PMID 39337613, 2024). "There was a decrease in DDIT3 expression (DDIT3 = 1.56 ± 1.0 vs. 0.89 ± 0.25 for the control group and the cancer group, respectively, p = 0.01) and no change in IL-6 expression between the control group and cancer group sera mixtures (IL6= 0.51 ± 0.19 vs. 0.55 ± 0.20, p = 0.7)." (PMID 36980729, 2023). "The mRNA levels of DDIT3, pERK, and ATF3 were highly upregulated upon 6-AN treatment in H460 cancer cells; however, XBP1 was not." (PMID 34827081, 2021).